KNG1 (kininogen 1)
Diseases named in the same sentence as KNG1 in open-access papers (continued):
Sharing a sentence is not in itself a finding about the gene and the disease.
type 2 diabetes (5 papers, 2013 to 2026). "Results suggest that elevated serum KNG-1, HSPG and Robo4 levels in type 2 diabetic patients might reflect a DN progressive pathology due to various mechanisms." (PMID 42310331, 2026).
glaucoma (4 papers, 2017 to 2025). Increased pressure in the eyeball due to obstruction of the outflow of aqueous humor. "Kininogen-1 was linked to the inflammatory and proliferative changes observed in various ocular diseases, including diabetic macular edema, diabetic retinopathy, glaucoma, uveitis, and age-related macular degeneration." (PMID 41402737, 2025).
preeclampsia (4 papers, 2012 to 2025). Preeclampsia is a hypertensive disorder of pregnancy that is characterized by new-onset hypertension with proteinuria presenting after 20 weeks of gestation, and depending on mild or severe forms may initially present with severe headache, visual disturbances, and hyperreflexia. "Apolipoprotein M (APOM) has been reported to be a diagnostic marker for preeclampsia, whereas serum peptides derived from kininogen-1 (KNG1) were part of a panel able to differentially diagnose preeclamptic pregnancies." (PMID 40974471, 2025).
Arthritis (3 papers, 2018 to 2019). Inflammation of a joint. "Kininogen 1 has been detected in numerous pathophysiological conditions, such as arthritis and inflammatory bowel disease." (PMID 31379949, 2019). "Studies on KNG1‐deficients mice demonstrated an important role of this protein in the pathogenesis of autoantibody‐induced arthritis, proposing the block of KNG1 cleavage as a novel therapeutic strategy for rheumatoid arthritis treatment (Xie, Dai, & Wu, 2016)." (PMID 30244532, 2018).
coagulation disorder (3 papers, 2017 to 2025). "Our experiment suggested that YCL treatment could downregulate the level of kininogen-1, which contributed to blood coagulation disorder in hyperlipidemia." (PMID 28883884, 2017).
hepatitis B (3 papers, 2022 to 2023). "Our whole-exon association study of 300 families with hepatitis B infection found that SNP rs76438938 in KNG1 significantly increased the risk for HBV infection, and the rs76438938-T allele was found to promote HBV replication by increasing the stability of KNG1 mRNA." (PMID 37442062, 2023).
IgA nephropathy (3 papers, 2010 to 2023). "Moreover, other diseases like interstitial cystitis or IgA nephropathy are also related to non-standard urine concentrations of kininogen-1." (PMID 28683725, 2017). "However, reduced KNG1 levels may not be cancer-specific since decreased levels have also been reported in the urine of patients with chronic pancreatitis, interstitial cystitis and IgA nephropathy." (PMID 37371512, 2023).
ischemic stroke (3 papers, 2017 to 2025). A stroke disorder caused by obstruction of blood flow to the brain, due to thrombotic (local blood clot formation) or embolic (due to a blood clot or other material traveling from another site) event. "Therefore, the most significant 4 genes were PIK3CA, IL6, TNF, and KNG1, which means these molecules may function as important immune regulators in the inflammatory response following ischemic stroke." (PMID 35419038, 2022).
kininogen deficiency (3 papers, 2018 to 2025). "KNG1 has been associated with diseases including high molecular weight kininogen deficiency and angioedema." (PMID 29884837, 2018).
rheumatoid arthritis (3 papers, 2018 to 2023). A chronic, systemic autoimmune disorder characterized by inflammation in the synovial membranes and articular surfaces. "Kininogen-1 and bradykinin expressions were altered in the synovial fluid of rheumatoid arthritis and osteoarthritis patients." (PMID 30555396, 2018).
Sepsis (3 papers, 2020 to 2022). Sepsis is defined as life-threatening organ dysfunction caused by a dysregulated host response to infection. "The induction of experimental sepsis by Streptococcus pyogenes was associated with a reduction of FXII, kininogen-1 and PPK in mice." (PMID 32867272, 2020).
type 1 diabetes (3 papers, 2017 to 2021). "Elevated expressions of kininogen-1 respectively prekallikrein (cleaves kininogen to vasoactive peptide bradykinin) have also previously been described in type 1 diabetic patients and rats, which in rats further could be reversed with insulin treatment." (PMID 34580391, 2021). "KNG1 fragments possess biological activity with moderate to strong correlation with specific diseases (i.e., early progressive renal function decline with type 1 diabetes), while those of murine A2M increase during inflammatory responses and tumor growth." (PMID 28592917, 2017). "Furthermore, the minor alleles of the KNG1 rs5030062 and rs710446 variants, which are associated with increased plasma pre-kallikrein and/or FXI levels, were associated with higher eGFR in the FinnDiane cohort of 4400 individuals with type 1 diabetes." (PMID 32270254, 2020).
viral infection (3 papers, 2019 to 2024). "Based on previous studies, we chose several factors in the present hemorrhage disease caused by a viral infection, including the coagulation factors: kininogen-1 (kng-1), f2, f3a, f3b and f10, as well as the anticoagulation factors: serine protease inhibitor (serpin) b1, c1, d1, f1, f2b, and g1." (PMID 31888180, 2019).
autoimmune disease (2 papers, 2018 to 2026). A disorder resulting from loss of function or tissue destruction of an organ or multiple organs, arising from humoral or cellular immune responses of the individual to their own tissue constituents. "Moreover, the underexpression of A1AT and the upregulation of KNG1 are reflective of a greater risk for HS‐RLS patients to develop CVD; these proteins may represent potential early diagnostic biomarkers for cardiovascular and autoimmune disorders." (PMID 30244532, 2018).
colitis (2 papers, 2019 to 2025). Inflammation of the colon. "KNG1 played a critical role in the pathogenesis of colitis in an animal mouse model for inflammatory bowel disease." (PMID 31623319, 2019). "In these mice, lack of KNG1 reduced colitis development, infiltration of inflammatory cells into the gut mucosa, and inflammatory cytokine levels (e.g., TNFα, IFN-γ, IL-1β, and IL-6)." (PMID 31623319, 2019).
Hepatic fibrosis (2 papers, 2021 to 2022). The presence of excessive fibrous connective tissue in the liver. "Kng1 gene expression is likely to be linked to liver fibrosis as supported by studies showing the inhibition of thrombin-induced platelet aggregation by bradykinin in humans." (PMID 34566641, 2021). "To corroborate the results of liver fibrogenesis on the PKKS effectors (plasma kallikrein and KNG1) and thrombin in chronic liver injury, we studied different time points of CCl4-induced liver fibrosis (4, 6, and 7 weeks)." (PMID 34566641, 2021). "This development among Kng1, Bdkrb1, and Bdkrb2 gene expressions, and myofibroblast activators and chronic liver injury creates a new direction in the study of liver fibrosis and its resolution." (PMID 34566641, 2021). "The degree of plasma kinkinin reduction is directly related to the severity of liver function impairment, and KNG1 levels are lower in patients with hepatic fibrosis/cirrhosis than in those with non-hepatic fibrosis C." (PMID 35935258, 2022).
hepatocellular carcinoma (2 papers, 2016 to 2024). A malignant tumor that arises from hepatocytes. "Increased KNG1 levels were detected in sera of patients with hepatocellular carcinoma." (PMID 26831905, 2016).
Insulin resistance (2 papers, 2012 to 2019). Increased resistance towards insulin, that is, diminished effectiveness of insulin in reducing blood glucose levels. "Proteins involved in inflammation (FIBA, TRFE, and KNG1) and insulin resistance (ARL15 and RET4) were abundantly excreted in the urine samples of metabolically unhealthy obese individuals compared to the metabolically healthy obese individuals." (PMID 31623319, 2019).
kidney damage (2 papers, 2022 to 2023). "In fact, previous proteomic studies have associated differential expression of kininogen-1 with the evolution of microalbuminuria, thus allowing it to serve as an early marker of nephropathy associated with T1DM and T2DM15,17–19." (PMID 35610262, 2022).
lung disease (2 papers, 2017 to 2022). "A set of three most significantly upregulated proteins (HBB, CRP and SERPINA1) and four most significantly downregulated proteins (APOA2, AHSG, KNG1 and AMBP) were selected for validation in an independent cohort of IPF and other lung diseases using ELISA test." (PMID 28122020, 2017).
neuropathy (2 papers, 2018 to 2023). A disorder affecting the nervous system that manifests with pain, tingling, numbness, and/or muscle weakness. "Using GWA study, we found four SNPs in four genes (SNX8; PCP2; KNG1; and RORA) to be statistically significantly associated with neuropathy." (PMID 29884837, 2018).
oral squamous cell carcinoma (2 papers, 2020 to 2024). "Additionally, KNG1 was identified as a serum biomarker for the early detection of advanced CRC and oral squamous cell carcinoma." (PMID 38902713, 2024).
Osteopenia (2 papers, 2011 to 2019). Osteopenia is a term to define bone density that is not normal but also not as low as osteoporosis. "However, the opposite was observed for serum protein levels of KNG1, where higher levels were observed in osteopenia." (PMID 31766436, 2019).
thyroid cancer (2 papers, 2021). "KNG1 is believed to be related to the occurrence of thyroid cancer." (PMID 34493981, 2021).
acute GVHD (1 paper, 2022). "Wang and colleagues (2018) reported that high KNG1 may damage tissue and may be upregulated in the gastrointestinal tract of acute GVHD." (PMID 36403426, 2022).
African trypanosomiasis (1 paper, 2021). "Of the 38 African trypanosomiasis ID5143 pathway genes nine could not be detected including Kng1 and 2 encoding the kallikrein-kinin hormonal cascade in addition to Il12b and the E-selectin gene Sele while the levels Il12a, Apoa1, Fasl and Plcb2 message were subthreshold." (PMID 34762691, 2021).
aneurysm (1 paper, 2009). Bulging or ballooning in an area of an artery secondary to arterial wall weakening. "We observed downregulation of the genes encoding kininogen (kng1), Apolipoprotein CI (Apoc1) and the neutrophil-associated leucine-rich alpha-2-glycoprotein 1 (Lrg1) amongst others, in aortas of mice resistant to aneurysm suggesting that they may be pathological genes." (PMID 19580648, 2009).
anxiety disorder (1 paper, 2019). A category of psychiatric disorders which are characterized by anxious feelings or fear often accompanied by physical symptoms associated with anxiety. "To investigate whether genetic variants in the KKS genes associate with anxiety disorders, we genotyped SNPs from KNG1, BDKRB1, and BDKRB2 in anxiety disorder cases (n = 321) and carefully matched controls (n = 653) from the Finnish population-based Health 2000 Survey." (PMID 31857655, 2019). "Of the 21 analysed KNG1 SNPs, 17 BDKRB1 SNPs, and 20 BDKRB2 SNPs, 5, 8, and 1 associated with anxiety disorders at the nominal p < 0.05 level, respectively." (PMID 31857655, 2019). "In human genetic association analysis, variants in genes for the bradykinin precursor (KNG1) and the bradykinin receptors (BDKRB1 and BDKRB2) were associated with anxiety disorders (p < 0.05)." (PMID 31857655, 2019). "Therefore, we systematically selected a comprehensive set of SNPs from the KNG1, BDKRB1, and BDKRB2 genes and genotyped them in a well-characterized Finnish anxiety disorder case-control sample, representative of the Finnish population." (PMID 31857655, 2019).
atherosclerosis (1 paper, 2014). A disease characterized by the build-up of fatty material and calcium deposition in the arterial wall resulting in partial or complete occlusion of the arterial lumen. "We hypothesize that decreased plasma levels of kininogen-1 could promote platelet aggregation and trigger the progression of atherosclerosis." (PMID 26038678, 2014).
babesiosis (1 paper, 2018). Babesiosis refers to a condition caused by microscopic parasites that infect the red blood cells. "Second in abundance was kininogen-1 with 19.9% of total intensity of TMT-labelled phosphopeptides in the control pool vs. 16.5% in the babesiosis pool." (PMID 30485286, 2018). "Moreover, significant differences in SAA, kininogen 1 and fibrinogen α phosphorylation levels were detected in canine babesiosis that could be useful as candidate biomarkers." (PMID 30485286, 2018).
bladder cancer (1 paper, 2023). "KNG1 levels were reduced in the samples of the bladder cancer patients." (PMID 37371512, 2023).
blood disease (1 paper, 2018). A disease that occurs in the blood. "The KNG1 was evidently enriched in extracellular exosome, plasma membrane and neuropiptide signaling pathway, suggesting that KNG1 was mainly involved in exocrine function and blood disease." (PMID 30068373, 2018).
colorectal tumor (1 paper, 2013). "This is supported by the immunohistochemistry results obtained that showed kininogen-1 accumulated in the cytoplasm of colorectal tumor cells." (PMID 23894665, 2013). "However, it remains unclear whether higher levels of kininogen-1 detected in the serum of patients with colorectal tumors derives from the colorectal tumor itself." (PMID 23894665, 2013). "Moreover, mechanistic studies of kininogen-1 in colorectal tumors are warranted." (PMID 23894665, 2013).
endometrial cancer (1 paper, 2024). Primary or metastatic malignant neoplasm involving the endometrium (mucous membrane that lines the endometrial cavity). "Urine samples from newly diagnosed endometrial cancer and healthy women that were resolved in 2-DE maps originating seven clusters were identified as KNG1, MPG, AZGP1, CD59, AMBP, IgG3C, and IgKC." (PMID 39194522, 2024). "In endometrial cancer patients, the expression of ABCG, ATR, CLU, and LRG1 was upregulated, while the expression of SERPINA1 and KNG1 was downregulated." (PMID 39194522, 2024).
fibromyalgia (1 paper, 2020). A chronic disorder of unknown etiology characterized by pain, stiffness, and tenderness in the muscles of neck, shoulders, back, hips, arms, and legs. "Elevated levels of proteins involved with acute phase signaling have been found in fibromyalgia and increased KNG1 was found associated with pain in women with chronic widespread pain." (PMID 32692761, 2020).
Headache (1 paper, 2021). Cephalgia, or pain sensed in various parts of the head, not confined to the area of distribution of any nerve. "Increased KNG1 levels were also detected in serum of MOH patients vs. non-headache controls." (PMID 33923220, 2021).
hypersensitivity pneumonitis (1 paper, 2017). Hypersensitivity pneumonitis (HP) is a pulmonary disease with symptoms of dyspnea and cough resulting from the inhalation of an antigen to which the subject has been previously sensitized. "Besides, KNG1 could serve as a biomarker for discriminating between IPF and healthy controls and IPF and hypersensitivity pneumonitis, but could not help discriminate between IPF and sarcoidosis." (PMID 28122020, 2017).
intraepithelial neoplasia (1 paper, 2013). A precancerous neoplastic process that affects the squamous, glandular, or transitional cell epithelium without evidence of invasion. "While cytoplasmic accumulation of kininogen-1 was found to negatively correlate with tissue histology for ACA patients (rs = -0.250, P = 0.029), it did not correlate with tumor location, tumor size, or grade of intraepithelial neoplasia (all P>0.05)." (PMID 23894665, 2013).
leprosy (1 paper, 2018). Leprosy is a chronic infectious disease affecting primarily the skin and peripheral nervous system. "More important, the absence of kininogen 1 in the leprosum clot, which deficiency was already associated with prolonged aPPT, could be a reasonable explanation for the observation of prolonged aPPT in leprosy patients." (PMID 29565968, 2018).
leukemia (1 paper, 2013). A malignant (clonal) hematologic disorder, involving hematopoietic stem cells and characterized by the presence of primitive or atypical myeloid or lymphoid cells in the bone marrow and the blood. "In addition, KNG1 and FCN3 potentially served as distinctive biomarkers for leukemia aggressiveness, whereas GELS played a restraining role as a suppressor protein in HR-ALL cases." (PMID 23849470, 2013).
liver disease (1 paper, 2024). "By training random forest models, a biomarker panel comprising KNG1, F11, KLKB1, CAPNS1, CDH1, CPN2, NME2, was identified by feature selection for liver disease detection." (PMID 39207047, 2024).
lung squamous cell carcinoma (1 paper, 2023). "In the down-regulated protein module, core protein KNG1 is known associated with tumorigenesis and has been reported as a novel biological fluid biomarker in lung squamous cell carcinoma." (PMID 38095636, 2023).
malignant glioma (1 paper, 2018). A grade III or grade IV glioma arising from the central nervous system. "Therefore, KNG1 might exert therapeutic effects on the malignant glioma." (PMID 30068373, 2018).
meningitis (1 paper, 2015). A disorder characterized by acute inflammation of the meninges of the brain and/or spinal cord. "As a consequence, only the aetiology-specific spot of the intersection subset of patients with meningococcal meningitis corresponding to kininogen-1 was eligible to integrate the qualitative predictive model for differential diagnosis of meningitis." (PMID 26040285, 2015). "This is the first report of increased CSF levels of kininogen-1 in patients with meningitis." (PMID 26040285, 2015).
meningococcal meningitis (1 paper, 2015). "Finally, at the third node, the presence of kininogen-1 is associated with meningococcal meningitis, and its absence, with pneumococcal meningitis." (PMID 26040285, 2015).
metastatic tumor (1 paper, 2023). "Downregulated KNG1 was also identified in metastatic tumor-draining lymph from metastatic mammary carcinoma through LC/MS proteomic analysis." (PMID 37719007, 2023).
nasopharyngeal carcinoma (1 paper, 2025). A carcinoma arising from the nasopharyngeal epithelium. "Furthermore, we found that the core genes of the nasopharyngeal carcinoma radiosensitivity signature (NPC-RSS), namely SMARCA2, DMC1, CD9, PSG4, and KNG1, had significant correlations with previously published genes related to radiosensitization." (PMID 40530955, 2025).
periodontal (1 paper, 2016). "In the present study, we found that HP, KNG1, A1AT and IGKC were differentially expressed in sera collected from periodontal patients." (PMID 27635317, 2016).
prediabetes (1 paper, 2020). "In contrast, carbonic anhydrase 1 (CAH1) and polypeptides from myelin expression factor 2 (MYEF2) 31 and kininogen-1 (KNG1) 32 showed specific abnormalities only in T2D but not in prediabetes." (PMID 32089734, 2020).
Pulmonary hemorrhage (1 paper, 2025). Pulmonary hemorrhage is a bleeding within the lungs. "In the lungs, ECSCR, KNG1, PLG, and transient receptor potential (TRP) cation channel subfamily C member 7 (TRPC7) were identified as factors that may contribute to pulmonary hemorrhage through various signaling pathways." (PMID 39764561, 2025).
sleep disorder (1 paper, 2018). A change from the patient's baseline sleeping pattern, in the hours slept and/or an alteration/dysfunction in the stages of sleep. "Expression of four proteins including PKM, CLU, KNG1 and PFN1 were changed by CSD and these proteins can potentially serve as biomarkers for sleep disorders." (PMID 30235220, 2018).
sudden cardiac arrest (1 paper, 2022). Unexpected rapid natural death due to cardiovascular collapse within one hour of initial symptoms. "Kininogen 1 is important in ACE-related pathways, and variations in KNG1 correlate with decreased risk of sudden cardiac arrest." (PMID 36312243, 2022).